ZEB1 (zinc finger E-box binding homeobox 1)
Diseases named in the same sentence as ZEB1 in open-access papers (continued):
Sharing a sentence is not in itself a finding about the gene and the disease.
pancreatic cancer (continued). "For instance, miR-205-5p suppresses the development of prostatic carcinoma cells via being regulated by p63 or targeting ZEB1; moreover, the cell progression of osteosarcoma and pancreatic cancer have been reported to be inhibited by miR-205-5p." (PMID 34996511, 2022). "According to genetic evidence from related studies, ZEB1 expression is essential for effective invasion and metastasis in mouse models of pancreatic cancer." (PMID 36076302, 2022). "To extend these observations, we examined localization of ZEB1 in control and O-GlcNAcylation inhibited pancreatic cancer cells." (PMID 35844792, 2022). "High expression of ZEB1 correlates with the mesenchymal cancer cells sensitivity to ferroptosis in non-small-cell lung cancer cells, head and neck cancer, pancreatic cancer cells and melanoma cells." (PMID 35844792, 2022). "Metastasis in many malignant tumors, such as pancreatic cancer, colon cancer and lung cancer, is related to expression of ZEB1 38-41." (PMID 35342335, 2022). "Our data concluded: miRNA-569 modulates the NUSAP1/ZEB1 signaling axis, exert anti-tumor function, which is expected to be the clinical therapeutic target of pancreatic cancer." (PMID 35483343, 2022). "Consistently, our study also showed that Fbxo45 can regulate the expression of Zeb1 and N-cadherin in pancreatic cancer cells." (PMID 35279684, 2022). "It has been established that in breast and pancreatic cancer ZEB1-driven EMT downregulates the expression of the RBP and splicing regulator ESRP1 as part of a self-enforcing feedback loop." (PMID 36346211, 2022). "PANC1 and PaTU8988 also expressed higher level of ZEB1 among the pancreatic cancer cell line panel, which was decreased in glucose depletion culture condition." (PMID 35844792, 2022). "Phosphorylated STAT3 can directly binds to the promoter region of ZEB1 and induces the transcription of ZEB1 in pancreatic cancer cells." (PMID 35372504, 2022). "It has been reported that phosphorylation of STAT3 (Tyr705) contributes to ZEB1 up-regulation, which in turn subsequently induces expression of integrin α3 and integrin β1 in pancreatic cancer cells." (PMID 35372504, 2022). "The miR-200 and miR-203 reduce the chemoresistance in the pancreatic cancer cell, but overexpressed ZEB1 suppresses these miRNAs." (PMID 35686109, 2022). "The functional alliance between ZEB1 and YAP promotes the transcription of a common ZEB1/YAP target gene set, which represents a predictor of poor survival, therapy resistance, and increased metastatic risk in breast and pancreatic cancers." (PMID 35477522, 2022). "Compared to the control cells, the nuclear localization of ZEB1 was decreased in O-GlcNAcylation inhibition pancreatic cancer cells as shown by Immunoblotting and Immunofluorescence assays." (PMID 35844792, 2022). "Knockdown of lncRNA XIST counteracts the effect of ZEB1 by promoting metastasis through the upregulation of miR-429, which identified the critical axis of XIST/miR-429/ZEB1 in pancreatic cancer migration, invasion and EMT." (PMID 35819532, 2022). "Among the different EMT-TFs, ZEB1 was the first one that was investigated in pancreatic cancer as a link from EMT to stemness." (PMID 36076302, 2022). "In pancreatic carcinoma, only ZEB1 is highly relevant for tumor onset and progression, especially in regulating cancer cell plasticity and metastasis." (PMID 35844792, 2022). "For instance, LncRNA-BX111 recruits the TF YB1 to regulate the transcription of ZEB1 to foster the metastasis and progression of pancreatic cancer." (PMID 34858481, 2021). "EGF‐induced EMT seems to require the function of the RNA‐binding protein Musashi2 (MSI2) by interaction with ZEB1 to facilitate ZEB1‐ERK/MAPK signaling in pancreatic cancer." (PMID 34459003, 2021). "Previous studies have shown that the decrease in the expression of ZO-1 and Claudin-1 accelerates the invasion and migration of pancreatic cancer via a ZEB1-dependent transcription." (PMID 34631521, 2021).
pancreatic cancer (continued). "A previous study using siRNA to silence ZEB-1, a key EMT inducer, has shown that ZEB-1 silencing enhanced sensitivity to erlotinib in pancreatic cancer cells." (PMID 34552882, 2021). "The gene expression analysis of EMT markers Zeb1, Vimentin, and Col1a1 were significantly decreased in YFP sorted primary pancreatic cancer cell lines from KPC;ST mice, along with complete loss of Snai1 and Twist1." (PMID 33852841, 2021). "In human tissue samples and pancreatic cancer cell lines, there was an inverse relationship between Zeb-1 and E-cadherin expression." (PMID 33918146, 2021). "The inverse correlation of E-Cadherin and Zeb1 is well documented for EMT in pancreatic cancer, resulting in consequent resistance to the clinically widely used chemotherapies." (PMID 35003368, 2021). "It has been demonstrated that EMT-TF ZEB1 can activate EMT through the repression of miRs-200 which inhibit stemness in pancreatic cancer." (PMID 34451837, 2021). "In this study, we constructed both cellular and animal models to systematically investigate the signalling axis ZEB1/LINC00472/miR‐23a‐3p/FOXO3 in pancreatic cancer." (PMID 34363438, 2021). "Accordingly, hypoxia induced the association of YBX1 with zinc-finger E-box-binding homeobox 1 (ZEB1), a key regulator of the EMT, to promote metastasis of pancreatic cancer." (PMID 34440660, 2021). "Previously another study using a short hairpin knockdown of ZEB1 in mice has also highlighted the importance of ZEB1 in tumor cells dissemination and in the tumor cells capacity to initiate tumor in pancreatic cancer." (PMID 34451837, 2021). "For example, ZEB1 promotes tumorigenicity by repressing stemness-inhibiting microRNAs in pancreatic cancer cells, promoting migration of CSCs." (PMID 34809669, 2021). "The ZEB1/miR-200/BMI1 pathway was involved in pancreatic cancer stem cells, which explained how EMT enabled stemness." (PMID 34178686, 2021). "As reported, hypoxia-induced lncRNA-BX111 promoted metastasis and progression of pancreatic cancer through regulating ZEB1 transcription." (PMID 33469161, 2021). "MALAT1 promotes stem cell-like phenotypes of pancreatic cancer cells via upregulating the expression of ZEB1 and self-renewal-related factor Sox2." (PMID 34660566, 2021). "Similar results were obtained for pancreatic cancer, where ZEB1 expression is a key determinant of cancer cell stemness and the reciprocal ZEB1/miR‐200 feedback loop is controlling the expression of genes of stemness factors including BMI1 and SOX2." (PMID 34459003, 2021). "Mocetinonstat was also the only HDACi that demonstrated specific antagonism of ZEB1-mediated miR-203 repression in pancreatic cancer cells." (PMID 33803458, 2021). "Hypoxia-induced lncRNA-BX111 acts as an oncogene in pancreatic cancer through regulating ZEB1 transcription." (PMID 33824282, 2021). "Mocetinostat, an HDACi, efficiently reduced the expression of ZEB1 in pancreatic tumour cells, revealing a therapeutic effect of class I HDACis in treating EMT and metastasis of cancers." (PMID 34395273, 2021). "Collectively, our data suggested that the LINC00472 expression was suppressed by ZEB1 in the pancreatic cancer tissues and cells." (PMID 34363438, 2021). "The first mechanistic insights came from experiments in pancreatic cancer, which showed that knocking down Zeb1 leads to reduced tumorsphere-forming and tumor-initiating capacity." (PMID 34072345, 2021). "Additional studies reported that ZEB1 induces the binding of HDACs with the CHD1 promoter in human pancreatic cancers." (PMID 34395273, 2021). "Specifically, biochemical and molecular analyses on pancreatic cancer cell models have shown an upregulation of ZEB1 target genes and a downregulation of ZEB1 protein level." (PMID 32429325, 2020).
pancreatic cancer (continued). "In pancreatic cancer, Rho associated coiled coil containing protein kinase 2 (ROCK2) enhances the expression of ZEB1." (PMID 32664703, 2020). "In summary, MSI2 accelerates the development and progression of pancreatic cancer through a novel ISYNA1‐p21/ZEB‐1 pathway, which supplies a novel gene targets in the PC treatment." (PMID 32779876, 2020). "Mocetinostat interferes with ZEB1, downregulating its mRNA and protein levels, and upregulates tumor-suppressing miR-203, resulting in significantly enhanced sensitivity of pancreatic cancer cells to gemcitabine therapy." (PMID 32266287, 2020). "In pancreatic cancer cells, the transcription factor ZEB1 plays a key role inthe regulation of EMT and the metastatic process by suppressing the E-cadherinexpression via the recruitment of HDAC1 and HDAC2 deacetylases to the promoterregion of the CDH1 gene." (PMID 33173593, 2020). "YB-1 was reported to be recruited by lncRNA-BX111887 at the promoter region of Zeb1, upregulated Zeb1 transcription, and promoted cell invasion and metastasis in pancreatic cancer." (PMID 33379356, 2020). "For instance, miR-429 was found to inhibit EMT through ZEB1 inhibition and its expression is typically down regulated in pancreatic cancer cells." (PMID 32664703, 2020). "As recent data indicate that ZEB1 is a critical player in pancreatic cancer metastasis, substantially more investigations are needed to elaborate on the role of the P2Y12–ZEB1 axis in cancer invasion and metastasis." (PMID 31968611, 2020). "Here, we took the chip-seq of ZEB1 in pancreatic cancer cell line as an example for further analysis." (PMID 31019894, 2019). "We also assessed ZEB1 expression in these cells since forced GLI2 expression has been shown to increase ZEB1 expression in pancreatic cancer cells." (PMID 31661013, 2019). "S100A14 is an epithelial protein, expressed exclusively in epithelial pancreatic cancer cell lines, and repressed by ZEB1." (PMID 31123345, 2019). "Our in vitro data confirmed previous studies which demonstrated its role in the EMT of pancreatic cancer cells as well as its cellular downstream effects by targeting ZEB1 and TWIST1." (PMID 31080555, 2019). "In our study, we first discovered ROCK2 induced ZEB1-conferred gemcitabine resistance in pancreatic cancer cells." (PMID 31783584, 2019). "In this context, RSV downregulates the EMT-inducting transcription factor (including Zeb-1, Slug and Snail) to reduce migration and invasion in pancreatic cancer cells." (PMID 31417401, 2019). "Mechanically, a novel sp1/p38/ZEB1 regulatory network was found to be involved in ROCK2-mediated gemcitabine resistance in pancreatic cancer cells." (PMID 31783584, 2019). "Previous studies have demonstrated that expression of ZEB1 is correlated with advanced tumor grade and poor outcomes in pancreatic cancer." (PMID 29416615, 2018). "Mechanistically, rfhSP-D downregulates the EMT-related gene signatures (Vimentin, Zeb1, and Snail), and hence, pancreatic cancer cells invasion, mainly by attenuating TGF-β signaling pathway." (PMID 30158928, 2018). "Knockout of Zeb1 had detrimental effects on cell plasticity and fixed pancreatic tumor cells in an epithelial state." (PMID 29903049, 2018). "Aberrant activation of EMT has been attributed to over-expression of mesenchymal markers, such as Zeb1 (zinc finger E-box binding homeobox 1), Snail, and Vimentin, as well as repression of E-cadherin, an epithelial marker in the pancreatic cancer cells." (PMID 30158928, 2018). "Previously, there have been two studies that investigated the prognostic value of stromal ZEB1 in pancreatic cancer." (PMID 29416615, 2018). "In particular, whereas the miR-200 family is known to exert tumor suppressor activity by silencing ZEB1 and ZEB2, ZEB1 has been reported to down-regulate miR-200 expression in the context of a mutual repression loop, in breast, colon and pancreas cancers." (PMID 30542509, 2018).
pancreatic cancer (continued). "ZEB1 in turn suppress the expression of the miR-200 family that leads to maintenance of pancreatic cancer stemness and induces EMT known to be responsible for paclitaxel resistance in pancreatic cancer patients." (PMID 29967761, 2018). "In pancreatic cancer, ZEB1 is the critical link between the activation of EMT and the acquisition of stem‐like properties and functions by suppressing miR‐200 family members, which are strong inducers of epithelial differentiation." (PMID 28649800, 2017). "Collectively, our results demonstrate that miR-145 targets MMP3, as well as Oct4, Lin28, Nanog, Sox2 and ZEB1 which are upregulated by linc-DYNC2H1-4 in pancreatic cancer cells." (PMID 28703793, 2017). "High expression of ZEB1 and vimentin, and low exprssion of E-cadherin, were verified in pancreatic cancer cell lines with intrinsic gemcitabine resistance, AsPC-1 and PANC-1." (PMID 28703793, 2017). "When mir-675-5p mimics and siUBQLN1 were co-transfected into the pancreatic cancer Patu8988 cells, the expression of ZEB1 protein was increased." (PMID 28212565, 2017). "ZEB1 enforces CD44 isoforms (CD44s) splicing by repression of epithelial splicing regulator ESRP1 in pancreatic cancer." (PMID 28245823, 2017). "Isoflavone treatment increased the expression of miR-200b, miR-200c, miR-let-7b, miR-let-7c, miR-let-7d, and miR-let-7e resulting in reduced levels of their target proteins zinc finger E-box-binding homeobox 1 (ZEB1) and vimentin in pancreatic cancer cells." (PMID 28955205, 2017). "In pancreatic cancer, downregulation of E-cadherin occurs through ZEB1, which recruits HDAC1 and HDAC2 to the CDH1 promoter to silence its expression." (PMID 26905733, 2016). "Gene set enrichment analysis (GSEA) of ZEB1-dependent genes in breast, colon and pancreatic cancer cells revealed gene sets strongly enriched compared with ZEB1 knockdown cells." (PMID 26876920, 2016). "From this result, we assumed that HS-173 had a strong correlation between the downregulation of TGF-β-induced EMT and the inhibition of ZEB1 in pancreatic cancer cells." (PMID 27793006, 2016). "DIM also decreased the expression of mesenchymal markers ZEB1, vimentin and Slug and changed the morphology of pancreatic cancer cells into the epithelial form." (PMID 27231938, 2016). "In this context, the class I HDAC inhibitor mocetinostat was recently shown to inhibit the expression of ZEB1, to upregulate its target, miR‐203, and to restore sensitivity to chemotherapy in pancreatic cancer cells." (PMID 27596438, 2016). "Overexpression of miR-200c increased the sensitivity to gemcitabine in the ZEB1-expressing, resistant pancreatic cancer cell lines Panc1 and MiaPaca (Fig1B and C)." (PMID 25872941, 2015). "To further identify the downregulated miR-652 and increased ZEB1 contributing to metastasis in pancreatic cancer, we detected the miR-652 and ZEB1 expression in pancreatic cancer and normal pancreas tissue samples." (PMID 26498682, 2015). "As the pH value decreased, ZEB1 expression significantly increased both in mRNA and protein levels in pancreatic cancer cell lines." (PMID 26498682, 2015). "For example, a report indicates that ZEB1 inhibits the expression of the miR-200 family, resulting in upregulation of polycomb protein Bmi1 and induction of stemness in pancreatic cancer." (PMID 25749385, 2015). "The present study displayed that the remarkable increase of ZEB1 was observed in pancreatic cancer cells treated with acidity, while knockdown of ZEB1 induced MET-like transformation in acidity treated pancreatic cancer cells." (PMID 26498682, 2015). "Accumulative evidences illustrated that ZEB1 plays critical roles in EMT of cancers including pancreatic cancer." (PMID 26498682, 2015).
pancreatic cancer (continued). "The results showed miR-652 was significantly decreased in pancreatic cancer tissues and negatively correlated with the upregulated ZEB1 expression." (PMID 26498682, 2015). "E-cadherin (CDH1 gene) is suppressed in several cancer types including pancreatic cancer by its repressors ZEB1 (zinc finger E-box-binding homeobox 1) and SIP1 (Smad-interacting protein 1, ZEB2, and SMADIP1) which thus act as EMT-activators." (PMID 25960741, 2015). "There was a correlation between poor differentiation, Snail and ZEB1 expression levels and sphere-forming capacity in these two pancreatic cancer cell lines." (PMID 24489910, 2014). "The inverse correlation between ZEB1 and E-cadherin has been reported in metastatic liver cancer cell lines and pancreatic tumor cell lines." (PMID 25197668, 2014). "In pancreatic cancer, E-cadherin suppression is significantly correlated with ZEB1 and ZEB2 expression level and poor prognosis." (PMID 25197668, 2014). "We found the expressions of N-cadherin, vimentin and ZEB1 were up-regulated, while the expression of E-cadherin exhibited down-regulation at mRNA levels in CSCs of pancreatic cancer cell line PANC-1." (PMID 24521357, 2014). "Ectopic expression of miR-200c induces higher levels of E-cadherin in breast and pancreatic cancer cells through the direct targeting of transcription factor 8 (TCF8/ ZEB1), a negative regulator of E-cadherin." (PMID 24204560, 2013). "We compared EPCAM mRNA levels in MDA-MB231 breast and Panc-1 pancreatic cancer cell clones with stable short hairpin RNA-mediated knockdown of ZEB1 (shZEB1 clones) to that in control knockdown (shGFP) clones." (PMID 23667256, 2013). "More specifically, in pancreatic cancer cells ZEB1 represses miR-203, which is an inhibitor of stemness, and the miR-200 family members miR-141, miR-200a, b, c, and miR-429, which also regulate expression of stem cell factors." (PMID 24213498, 2012). "Hypoxic pancreatic cancer cells exhibited substantial upregulation of Twist, Snail, Zeb1, and Zeb2 as compared with normoxic cells." (PMID 21887310, 2011). "In the present study, resveratrol inhibited the expression of Snail, Slug and Zeb-1 in pancreatic cancer stem cells." (PMID 21304978, 2011). "We showed that overexpression of miR-141 and miR-200c led to reduced expression of CtBP2 and ZEB1 in human pancreatic carcinoma (PANC-1) cells." (PMID 21867514, 2011). "This relationship was validated prospectively in five additional pancreatic cancer cell lines that were analyzed according to their Zeb1 levels." (PMID 24281219, 2010). "In summary, these observations suggest that the majority of human pancreatic cancer cells are addicted to K-ras, but K-ras dependency can be overridden by ZEB1-induced EMT." (PMID 24281177, 2010). "Here we review the biological functions of ZEB1 and its role in cancer, especially pancreatic cancer." (PMID 24281177, 2010). "ZEB1 is expressed at the invasive front of pancreatic cancer and highly correlates with the expression of miR-200 family members and miR-203." (PMID 24281178, 2010). "In one study, tissue microarray analysis of pancreatic cancer showed an inverse relationship between Zeb1 and E-cadherin expression." (PMID 24281219, 2010). "Knockdown of ZEB1 in two highly aggressive pancreatic cancer cell lines resulted in a reduction of tumorigenicity in limiting dilution assays as well as reduced tumor dissemination in an orthotopic nude mouse model." (PMID 24281177, 2010). "In pancreatic cancer, ZEB1 upregulation is a key factor in promoting metastasis." (PMID 39941895, 2025). "Promotion of pancreatic cancer cell invasion through the microRNA-569/NUSAP1/ZEB1 axis." (PMID 40535133, 2025). "Additionally, O-GlcNAcylation of ZEB1 has been shown to promote lipid peroxidation and ferroptosis in pancreatic cancer cells." (PMID 40771411, 2025).